CLDN4 (claudin 4)
Diseases named in the same sentence as CLDN4 in open-access papers (continued):
Sharing a sentence is not in itself a finding about the gene and the disease.
colitis (20 papers, 2015 to 2026). Inflammation of the colon. "Intestinal mucosal barrier destruction was associated with colitis progression; additionally, junction protein expression (occludin, ZO-1, and claudin-4) in the colon was determined by quantitative PCR and immunofluorescence." (PMID 31632373, 2019). "In addition, claudin-4 gene knockout [-/-] mice develop colitis-like symptoms associated with increased intestinal permeability." (PMID 39334888, 2024). "During colitis, a higher expression of Muc4 was maintained, and in addition, Cldn4, Ocln, and Jup, important tight and adherens junction components, were upregulated." (PMID 40471139, 2025). "A significant increase in mRNA expression for ZO-1 and Cldn8 and significant decrease in the expression of Cldn4 and Muc2 mRNAs were observed in the group of obese animals with colitis forced to participate in treadmill exercise (p < 0.05)." (PMID 38255781, 2024). "Claudin-4 protein levels were significantly reduced in the colitis group compared to the control group." (PMID 39334888, 2024). "The MFGM maintains tight junction protein expression, such as claudin-4 and zonula occludin-2, that aids with the maintenance of barrier integrity in a murine colitis model." (PMID 38612988, 2024). "As defective tight junction (TJ) integrity is a key pathology of colitis, in our following experiments, two main TJ components of intestinal barrier, occludin and Cldn4, were detected." (PMID 36776831, 2023). "Our data for disease activity index, colonic lipocalin-2 levels, and claudin-4 immunoreactivity showed an effective colitis-like pathophysiology in both the wild type and AppNL-G-F mice." (PMID 37511312, 2023). "Claudin-1, claudin-4 and claudin-7, which are normally expressed in the colon for TJ sealing, are observed reduced in acute colitis, CD and colitis patients." (PMID 36767519, 2023). "Comparison with the normal control group indicated that the DSS control group showed a reduction in the levels of claudin-4 and occludin within the colon of mice with colitis, and oral treatment with LAB partially reversed this decrease." (PMID 36187993, 2022). "VIP protects the distribution and levels of junction proteins (for example, ZO-1, occludin, claudin-3, and claudin-4) against colitis by inhibiting MLCK or PKCε." (PMID 34552687, 2021). "Additional induction of colitis evoked a downregulation of claudin-3 in both intestinal segments and an upregulation of claudin-4 in the jejunum." (PMID 30971956, 2019). "In line with our results, previous studies reported a disrupted and irregular expression pattern of tight junction proteins including occludin and claudin-4 in the colonic mucosa in mice with DSS-induced colitis." (PMID 26218284, 2015). "Moreover, HFCD intake has been associated with intestinal barrier alterations through the downregulation of tight junction proteins (occludin, ZO-1, and claudin-4) and gut dysbiosis, which exacerbate gastrointestinal symptoms in colitis models." (PMID 41425635, 2025). "Finally, claudin-4 isoform expression was significantly decreased in the colitis group compared to the untreated controls." (PMID 39334888, 2024). "Our study revealed that, in IAP-treated mice with colitis, both Cldn4 and Cldn8 were upregulated." (PMID 38255781, 2024). "When in addition to the sensitization a colitis was induced, a significant decrease in claudin-3 immunofluorescence was observed in both intestinal segments, whereas the immunofluorescence for claudin-4 was unchanged in the colon, but increased significantly in the jejunum." (PMID 30971956, 2019). "The mRNA expression of ZO-1, Cldn4 and Cldn8 was significantly increased while the Muc2 mRNA expression was significantly decreased in the IAP-treated forced-exercise TNBS colitis rats fed an SD (p < 0.05)." (PMID 38255781, 2024). "The symptomatic parameters of colitis, disease activity index (DAI), colonic lipocalin levels, and claudin 4 immunoreactivity were assessed after the second round of DSS treatment." (PMID 37511312, 2023).
colitis (continued). "Compared with the normal group, the expressions of the TJs were significantly reduced in the colitis group (P < 0.01 for JAM-1, P < 0.001 for occludin, and P < 0.001 for claudin-4)." (PMID 29849501, 2018). "Eliminating Akt1 from human IECs in vitro resulted in greater expression of occludin and claudin 4, and mice lacking GC-C exhibited lower levels of occludin and claudin-4, intestinal hyperpermeability and susceptibility to DSS-induced colitis." (PMID 40801095, 2025). "Expression of Cldn3, Cldn4, Cldn7 and Cdh1 mRNA was however not altered during colitis or due to the absence of Muc13 expression in mice." (PMID 37174625, 2023). "Nobiletin treatment of colitis, however, did not reverse colitis-induced reduction in claudin-4." (PMID 39334888, 2024). "The expression levels of these TJs in pretreated-Bifico-colitis and pretreated + treated-Bifico-colitis groups were extensively increased compared with the colitis group (P1 < 0.05 and P2 < 0.05 for JAM-1, P1 = 0.073 and P2 < 0.01 for occludin, and P1 = 0.598 and P2 < 0.05 for claudin-4)." (PMID 29849501, 2018).
endometrial cancer (16 papers, 2005 to 2025). Primary or metastatic malignant neoplasm involving the endometrium (mucous membrane that lines the endometrial cavity). "A change in claudin-1 and claudin- 4 expression is also associated with endometrial cancer." (PMID 32197343, 2020). "Because the function of CLDN4 was unclear in endometrial cancer, cells were transfected with two sequences of siRNAs against CLDN4." (PMID 34887379, 2021). "What’s more, Kaplan–Meier survival analysis indicated that endometrial cancer patients with higher CLDN4 expression appeared to have a shorter survival probability compared with those patients who expressed lower levels of CLDN4." (PMID 34887379, 2021). "Other mechanisms relevant to claudin-4 overexpression in endometrial cancer are still under investigation." (PMID 23599806, 2013). "In conclusion, this study was undertaken to understand the biological significance of altered claudin-4 expression in endometrial carcinoma." (PMID 23599806, 2013). "The relationship between therapy with anti-neoplastic agents and the expression of claudin-4 was also analyzed using an endometrial carcinoma xenograft model." (PMID 23599806, 2013). "Treatment significantly prolonged the survival of tumor-bearing mice, suggesting that CLDN3 and CLDN4 may represent promising therapeutic targets for the management of aggressive, treatment-resistant type II endometrial cancers." (PMID 40687428, 2025). "Recent findings suggest that miR-424-5p may promote endometrial cancer progression by modulating the CLDN4/PI3K/AKT signaling pathway." (PMID 39309825, 2024). "Claudins-3 (CLDN3 – claudin 3) and -4 (CLDN4 – claudin 4) were elevated in endometrial cancer." (PMID 39176196, 2024). "Next, we investigated CLDN4 expression in endometrial cancer and normal tissues using transcriptome data downloaded from TCGA datasets and discovered that CLDN4 exhibited higher expression in endometrial cancer than in normal tissues." (PMID 34887379, 2021). "In conclusion, we demonstrated that by acting as a significant target of miR-424-5p, SPTBN2 could interact with CLDN4 to promote endometrial cancer metastasis via PI3K/AKT pathway in EEC." (PMID 34887379, 2021). "Changes in claudin-4 location in endometrial cancer cells were also observed." (PMID 32197343, 2020). "In addition, intracellular CLDN4 translocation has been observed in rat reflux esophagitis model and estrogen treatment of endometrial cancer cells." (PMID 32481659, 2020). "Although EEC and USPC belong to two different pathogenetic types of endometrial carcinoma, these results have led to the suggestion that upregulated claudin-4 may be involved in endometrial carcinogenesis." (PMID 23599806, 2013). "Claudin-4 is a useful biomarker in the treatment of patients with endometrial carcinoma." (PMID 23599806, 2013). "The present observations raise the possibility of exploiting claudin-4 as a potential biomarker for endometrial carcinoma and may provide an opportunity for therapeutic intervention." (PMID 23599806, 2013). "Moreover, we found SPTBN2 could interact with CLDN4 to promote endometrial cancer metastasis via PI3K/AKT pathway." (PMID 34887379, 2021). "Thus, it is possible that LSR may be a potential targeting molecule in therapy for endometrial cancer like clostridium perfringens enterotoxin (CPE)-mediated therapy targeting claudin-4." (PMID 27036040, 2016). "For example, claudin-3 and claudin-4 were expressed at high levels in endometrioid adenocarcinoma and prostate cancer; claudin-10 expression was up-regulated in hepatocellular carcinoma and thyroid papilloma; claudin-2 has been reported to be up-regulated in thyroid cancer and endometrial cancer." (PMID 24245968, 2013). "In TCGA database, CLDN4 was highly expressed in CESC, CHOL, PCPG and endometrial carcinoma (UCEC), and the integration of GTEx database demonstrated that the expression level of CLDN4 was also markedly up-regulated in CESC, CHOL, PCPG and UCEC." (PMID 41461671, 2025).
endometrial cancer (continued). "In contrast to undifferentiated endometrial carcinomas, SDUS frequently has some residual benign endometrial glands, and it is microsatellite-stable with low expression of Claudin-4/CK/EMA." (PMID 37194064, 2023). "In addition, although the overall levels of CLDN-4 protein were lower compared with those of CLDN-3, we also observed overexpression of CLDN-4 in the EFE-184, MES-SA, MFE-296, MFE-319 and RL95-2 endometrial cancer cell lines relative to THESCs." (PMID 36484008, 2022). "In addition to the expected frequent overexpression of the much studied CLDN-3, CLDN-4 and OCLN genes, we also observed overexpression of an additional 21 TJ genes in at least one of the endometrial cancer cell lines." (PMID 36484008, 2022). "Claudin-6 and claudin-4, which are absent in normal adult samples, are aberrantly expressed in endometrial cancer." (PMID 36091010, 2022). "In this study, we investigated the expression and the clinical values of SPTBN2 in endometrial cancer, and we mainly explored the biological functions and the potential interaction among miR-424-5p, SPTBN2 and CLDN4, and identified their effects on progression in endometrial cancer." (PMID 34887379, 2021). "Moreover, the expression of claudin-4 is upregulated, while claudin-1 is downregulated as compared to normal endometrial cells, indicating that these proteins might be involved in endometrial tumorigenesis and could be helpful during the diagnosis of endometrial cancer." (PMID 32197343, 2020).
mesothelioma (13 papers, 2013 to 2025). A usually malignant and aggressive neoplasm of the mesothelium which is often associated with exposure to asbestos. "Reports assessing Claudin-4 in non-small cell lung cancer revealed mild positive results in 469 of 502 (93%) carcinomas and five of 463 (1.0%) epithelioid/biphasic mesotheliomas (sensitivity 93%, specificity 98.9%)." (PMID 40091315, 2025). "These alterations in claudin expression are in contrast to findings reported in analyses of pleura cancer and mesothelioma, which show an alteration of claudin-4." (PMID 25009499, 2014). "CLDN4 expression is specific and sensitive for metastatic carcinoma vs. mesothelioma." (PMID 40687428, 2025). "Hence, CLDN4 can be used as a tumor marker to differentiate neoplastic metastases from mesothelioma." (PMID 38731853, 2024). "Furthermore, claudin-4 is negatively expressed in reactive mesothelial cells and mesothelioma, differentiated from PCa, while it is significantly positively expressed in plasma membrane metastases and primary carcinoma of PCa." (PMID 36959784, 2023). "Therefore, claudin-4 can be used as an IHC reagent to exclude mesothelioma diagnosis." (PMID 36959784, 2023). "Churg and Naso have recently hypothesized that the use of only two immunostains usually could enable the highly accurate differentiation between epithelioid/biphasic mesotheliomas from NSCLC carcinomas using HEG1 and Claudin-4 IHC labelling in combination." (PMID 40091315, 2025). "They discovered that all benign effusion patients with RMCs tested negative for Claudin-4, while only one mesothelioma case (1.6%) and 131/137 (95.6%) adenocarcinoma cases (including all 34 cases of lung adenocarcinoma) tested positive." (PMID 40091315, 2025). "They discovered that all mesotheliomas and benign effusions with RMCs tested negative for Claudin-4, but 100% of adenocarcinomas tested positive." (PMID 40091315, 2025). "In an immunohistochemistry (IHC) study of CLDN4 in pleural and peritoneal fluid or tissue biopsies, the CLDN4 stain was strongly positive in primary carcinoma and metastatic lesions but not in mesothelioma." (PMID 38731853, 2024). "Based on the excellent sensitivity and specificity of this simple “double-hit” (Claudin-4 and BAP1) panel for discriminating mesothelioma with epithelioid features from conventional carcinoma, we replicated the same study design in the setting of sarcomatoid neoplasms, namely SM versus SC." (PMID 36673059, 2023). "We experienced an excellent value of the “two-hits” panel of Claudin-4 and BAP1 in the differential diagnosis between mesothelioma with epithelioid features and conventional metastatic carcinomas, demonstrating a 94% sensitivity, a 100% specificity and a 96% diagnostic accuracy." (PMID 36673059, 2023). "Our data consequently do not support replacement of claudin-4 by claudin-10 for differentiating HGSC from mesothelioma, nor its precedence over claudins 1, 3 or 7 as a second marker." (PMID 37067588, 2023). "According to that report, all mesotheliomas were negative for claudin 4, while almost all adenocarcinomas were positive in cytology specimens of pleural effusion." (PMID 36714681, 2023). "Recent studies demonstrated that Claudin-4 is by far the most helpful negative marker of mesothelioma in terms of sensitivity and specificity, and the best positive pan-carcinoma antibody." (PMID 36673059, 2023). "Interestingly, CLDN4 was positive for 100% of adenocarcinoma cases and negative for 100% of mesothelial and mesothelioma effusions." (PMID 38731853, 2024). "In this context, Claudin 4 was identified to be an important marker for carcinoma vs. mesothelioma diagnosis in pleural and peritoneal biopsies and effusions, as it is detected in metastatic tumor cells but not in benign forms of mesotheliomas." (PMID 25009499, 2014). "Among the negative mesothelioma markers, MUC4, CEA, Claudin 4, TTF-1, and Napsin-A showed 100% sensitivity, p40 showed 95.4%, P63 showed 76.9%, and CK5/6 showed 69.2%." (PMID 29317712, 2018).
mesothelioma (continued). "Pleura-based tumor spread was indeed reminiscent of mesothelioma; however, diffuse expression of p40, MOC31, and claudin 4 and negative expression of WT1 and D2-40 ruled out this possibility." (PMID 29625594, 2018).
ovarian tumor (13 papers, 2005 to 2025). "Given the association of claudin-4 with both the cell cycle and genomic instability in ovarian tumor cells, we evaluated cell-cycle progression." (PMID 39625235, 2025). "This concept is supported by our findings, which show a correlation between the expression of clustered proteins associated with claudin-4 and aggressiveness in ovarian tumors, ultimately resulting in reduced patient survival." (PMID 38867360, 2024). "We have shown here that loss of claudin-4 expression in ovarian tumor cells, expressing high levels of claudin-4, can reduce migration." (PMID 27724921, 2016). "The loss of claudin-4 expression in ovarian tumor cells produced the same pro-apoptotic and anti-migratory activity as DFYNP." (PMID 27724921, 2016). "Contrary to our observations, the Howell laboratory has shown that loss of claudin-4 expression in ovarian tumor cells enhances cell survival and inhibits migration." (PMID 27724921, 2016). "Although a direct interaction of claudin-4 with CD44 has yet to be confirmed, CD44 expression has been found to be associated with claudin-4 expression in particularly aggressive ovarian tumor cells." (PMID 23521713, 2013). "Furthermore, this dual role of claudin-4 was associated with ovarian tumor cell resistance to genome instability formation and cell death by a known genomic instability-inducing agent, such as the PARP inhibitor olaparib." (PMID 39625235, 2025). "Also, SLC1A5 and LAT1 inhibition resulted in autophagy upregulation in different ovarian tumor cells, suggesting an association of claudin-4 with these amino acid transporters as a potential element regulating autophagy." (PMID 38867360, 2024). "To better support the role of claudin-4 in F-actin localized at cell-to-cell junctions, we generated ovarian tumor cells expressing LifeAct (a marker of F-actin compatible with living cells)." (PMID 39625235, 2025). "Following claudin-4 downregulation, the cellular connections between ovarian tumor cells displayed increased mobility and progressively became more irregular, suggesting significant alterations in the plasticity of cell-to-cell interactions." (PMID 39625235, 2025). "To gain further insights into claudin-4’s role in genomic instability, we conducted a morphometric characterization of ovarian tumor cell nuclei during claudin-4 expression modulation and CMP treatment." (PMID 39625235, 2025). "Overall, our results show that claudin-4 significantly influences the progression of ovarian tumor cells through the cell cycle." (PMID 39625235, 2025). "Ovarian tumors with high claudin-4 expression displayed a 2-fold reduction in genomic instability compared with tumors with low claudin-4 expression, consistent with previous reports linking claudin-4 expression to reduced genetic mutations." (PMID 39625235, 2025). "Specifically, claudin-4 expression seems to arrest some ovarian tumor cells in the G0–G1 phase, resulting in fewer cells transitioning to the S-phase." (PMID 39625235, 2025). "For instance, ovarian tumors expressing claudin-4 exhibit stronger resistance to the accumulation of genetic alterations, potentially rendering tumor cells resistant to cell death by preventing excessive accrual of genome instability." (PMID 38867360, 2024). "Together, our results show that the upregulation of claudin-4 contributes to increasing the threshold of tolerance for genomic instability in ovarian tumor cells by limiting its accumulation through autophagy." (PMID 38867360, 2024). "This search aimed to unveil crucial cellular processes mediated by claudin-4 potentially relevant in ovarian tumors." (PMID 38867360, 2024). "Here, we demonstrate that claudin-4, traditionally described as a TJ protein, participates in a tolerance mechanism for genomic instability in ovarian tumor cells." (PMID 38867360, 2024). "Autophagy regulation via claudin-4/SLC1A5/LAT1 has the potential to be a targetable mechanism to interfere with genomic instability in ovarian tumor cells." (PMID 38867360, 2024).